CT45A10 (cancer/testis antigen family 45 member A10)
Tractability: No criterion of Open Targets' tractability assessment is met for any kind of drug.
Gene: Protein-coding gene on chromosome X (135,879,471 to 135,893,444, reverse strand). Ensembl gene ENSG00000269586.
Subcellular location: Nucleus
Subcellular location (Human Protein Atlas): Nucleoli; Nucleoplasm
Gene Ontology:
Molecular function: identical protein binding; protein binding
Cellular component: nucleus
Homologues: Orthologues: chimpanzee CT45A10 (96% identical), rat Ct45a9 (30% identical), mouse Ct45a (29% identical), Caenorhabditis elegans ints-6 (18% identical), Drosophila melanogaster IntS6 (17% identical). Paralogues in human: CT45A2 (95% identical), CT45A5 (95% identical), CT45A6 (95% identical), CT45A7 (95% identical), CT45A8 (95% identical), CT45A9 (95% identical), CT45A3 (94% identical), CT45A1 (94% identical), SAGE1 (34% identical), INTS6L (33% identical), INTS6 (28% identical).